NES (nestin)
Diseases named in the same sentence as NES in open-access papers (continued):
Sharing a sentence is not in itself a finding about the gene and the disease.
Hirschsprung disease (1 paper, 2014). Hirschsprung disease (HSCR) is a congenital intestinal motility disorder that is characterized by signs of intestinal obstruction due to the presence of an aganglionic segment of variable extent in the terminal part of the colon. "Nestin expression is also up-regulated in Hirschsprung's disease." (PMID 24780093, 2014).
Hypoglycemia (1 paper, 2023). A decreased concentration of glucose in the blood. "Consequently, Nestin-Cre;Tsc1fl/fl mice exhibit activated mTORC1 signaling in the brain, macrocephaly, and die at P0, likely because of malnutrition, hypoglycemia, and hypothermia." (PMID 36509146, 2023).
IgA nephropathy (1 paper, 2020). "Studies have shown that nestin expression in podocytes is closely related to the proteinuria in kidney diseases such as IgA nephropathy, membranous nephropathy (MN) and focal stage glomerulosclerosis." (PMID 32371936, 2020).
Infertility (1 paper, 2014). "Brain-specific ERα deletion using CamKIIα-Cre or nestin-Cre has previously been shown to cause elevated serum E2 levels and infertility." (PMID 24416430, 2014).
influenza (1 paper, 2023). An acute viral infection of the respiratory tract, occurring in isolated cases, in epidemics, or in pandemics; it is caused by serologically different strains of viruses (influenzaviruses) designated A, B, and C, has a 3-day incubation period, and usually lasts for 3 to 10 days. "Influenza-induced decreases in feeding, drinking, movement, body weight and survival were attenuated in Advillin-creER; Ptger3flox mice, with effect magnitudes similar to ibuprofen treatment, but persisted in Nestin-cre; Ptger3flox mice." (PMID 36890237, 2023). "We then crossed Ptger3flox mice with either Nestin-cre or Advillin-creER mice, which target Cre recombinase to most central or peripheral neurons, respectively, and measured influenza-induced sickness behaviours." (PMID 36890237, 2023).
Intellectual disability (1 paper, 2018). "A partly overlapping deletion in the 1q22-q23.1 region has been recently described in a patient presenting with intellectual disability and multiple congenital anomalies, and two of the HI genes, NES and MAF2D, were shown to be necessary for normal neuron development in mice." (PMID 29845577, 2018).
Intraventricular hemorrhage (1 paper, 2016). Bleeding into the ventricles of the brain. "We observed severe intraventricular hemorrhage (IVH) in Arpc2f/f Nestin-Cre mouse embryos at E15.5." (PMID 27385014, 2016).
invasive breast carcinoma (1 paper, 2020). A carcinoma that infiltrates the breast parenchyma. "Co-localization of nestin and MT1 in invasive breast cancer was associated with worse prognosis and advanced histological stage." (PMID 32467665, 2020).
invasive carcinoma (1 paper, 2017). A carcinoma that is not confined to the epithelium, and has spread to the surrounding stroma. "The highest expression of nestin was in the invasive carcinoma and lymph node metastatic carcinama." (PMID 29029411, 2017).
inverted papilloma (1 paper, 2021). An endophytic benign papillary epithelial neoplasm that results from the invagination and proliferation of epithelial cells in the underlying stroma. "In relation to the histological type, 100% of pleomorphic adenomas were positive for nestin with grade 3 intensity, 100% of polyps and inverted papillomas were negative (p < 0.001) and the rest of the histological varieties were positive in a variable pattern." (PMID 33805026, 2021). "We have found a positivity for nestin in head and neck region lesions of 37.5% globally, remaining negative in all inflammatory lesions (polyps) and inverted papillomas) and in 51% of malignant tumour lesions." (PMID 33805026, 2021).
kidney cancer (1 paper, 2018). Primary or metastatic malignant neoplasm involving the kidney. "We did find that higher nestin expression was associated with unfavourable kidney cancer prognosis, consistent with previous studies." (PMID 30279450, 2018).
Kidney Cyst (1 paper, 2017). Abnormal fluid filled sac within the kidney, either acquired or congenital. "Cell-specific loss of Tsc1 within nestin-expressing cells in adult mice leads to the formation of kidney cysts, renal intraepithelial neoplasia, and invasive papillary renal carcinoma." (PMID 29184052, 2017).
kidney failure (1 paper, 2009). An acute or chronic condition that is characterized by the inability of the kidneys to adequately filter the blood. "In agreement with this, the Pkd1Flox/ΔC;Nestin-Cre mouse developed renal cystogenesis and died of kidney failure around P12 (not shown)." (PMID 19774080, 2009).
large cell neuroendocrine carcinoma (1 paper, 2021). A usually aggressive carcinoma composed of large malignant cells which display neuroendocrine characteristics. "Nestin expression was immunohistochemically studied in 30 patients with resected large-cell neuroendocrine carcinoma (LCNEC), and its associations with clinicopathological parameters, the Ki-67 labeling index (LI), and TTF-1 expression were evaluated." (PMID 34943921, 2021).
leukoplakia (1 paper, 2019). A white patch or plaque on a mucous membrane that cannot be characterized clinically or pathologically as any other disease. "In an attempt to trace the earliest change in nestin upregulation, leukoplakia samples were also included for the study." (PMID 31675305, 2019). "To summarize, there is an upregulation of nestin expression in leukoplakia and OSCC samples, as determined by western blot and immunohistochemical techniques." (PMID 31675305, 2019). "In a total of 26 leukoplakia cases studied, 65% of cases showed positive expression for nestin in the epithelial cells." (PMID 31675305, 2019). "Among the leukoplakia samples, nestin-positive blood vessels were visualized in the sub-epithelial connective tissue." (PMID 31675305, 2019). "Nestin expression in leukoplakia samples suggests that it could be an early event in the multistage carcinogenesis of oral epithelium." (PMID 31675305, 2019). "Hence, to address this issue, the present study observed nestin expression in samples of normal mucosa, leukoplakia, and OSCC using western blot and immunohistochemical analysis." (PMID 31675305, 2019). "The mean expression of nestin in the blood vessels in NOM, leukoplakia, and OSCC were 0, 1.87±1.58, and 2.65±1.67, respectively, and a statistically significant difference was reached." (PMID 31675305, 2019). "Nestin expression was confined to the basal layer of the epithelium in NOM samples, whereas it was also seen in the suprabasal layers in leukoplakia samples." (PMID 31675305, 2019). "However, leukoplakia and OSCC samples showed nestin-positive vessels abundantly near the sub-epithelial area and invasive front of the tumor, respectively." (PMID 31675305, 2019).
lung squamous cell carcinoma (1 paper, 2014). "Here, we first established that nestin is expressed in 34.4% of ESCC samples in Chinese population, a result similar to that reported for lung squamous cell carcinoma (35.5%) and our previous findings in NSCLC." (PMID 24966803, 2014).
lymphangioma (1 paper, 2025). A benign lesion composed of dilated lymphatic channels. "In the present report, we used human haemangiomas and lymphangiomas, which are benign vascular lesions lined by a monolayer of endothelial cells, as models to study the nestin expression in blood and lymphatic vessels in situ." (PMID 40149541, 2025). "This study aimed to investigate the expression of nestin in haemangiomas and lymphangiomas to determine its potential role as a vascular marker." (PMID 40149541, 2025). "Thus, nestin-positive blood vessels served as an internal positive control for the nestin staining in lymphangiomas." (PMID 40149541, 2025). "Contrary to its relatively high expression in haemangiomas, almost no nestin expression was detected in the endothelium of the analyzed lymphangioma samples." (PMID 40149541, 2025). "The present study revealed that nestin is expressed in haemangiomas, but not in lymphangiomas." (PMID 40149541, 2025). "In contrast, endothelial cells in nine out of ten lymphangiomas were completely nestin-negative." (PMID 40149541, 2025).
lysosomal storage disease (1 paper, 2020). A metabolic disorder caused by mutations in proteins critical for lysosomal function, including lysosomal enzymes, lysosomal integral membrane proteins, and proteins involved in the post-translational modification and trafficking of lysosomal proteins. "To date, most insights on the mechanisms linking glycosphingolipids and neuroinflammation arise from experimental models of lysosomal storage diseases that show important enzymatic defects, including Gbaflox/flox; nestin-Cre and Hexb−/− mouse models." (PMID 33069254, 2020).
malignant vascular tumors (1 paper, 2025). "Previously, the expression rate of nestin was shown to be higher in capillary haemangiomas than in malignant vascular tumors." (PMID 40149541, 2025).
Merkel cell carcinomas (1 paper, 2019). "Another group reported that BCCs and Merkel cell carcinomas were negative for Nestin; however, 45% of SCC cases were Nestin positive." (PMID 31065284, 2019).
mesothelioma (1 paper, 2015). A usually malignant and aggressive neoplasm of the mesothelium which is often associated with exposure to asbestos. "Robust nestin immunoreactivity was observed in the biphasic mesothelioma cell line SPC212 and the MPM tumor tissues as well as in the immortalized mesothelial cell line MET5A (data not shown)." (PMID 26421614, 2015). "Herein, we found that most mesotheliomas (59–65%) were negative for nestin." (PMID 26421614, 2015).
metastatic prostate carcinoma (1 paper, 2013). A carcinoma that arises from the prostate gland and has spread to other anatomic sites. "Accumulating data also suggest that both vimentin and nestin may be the key players in the transition from androgen-dependent to castration-resistant metastatic prostate cancer." (PMID 24086245, 2013).
middle ear cholesteatoma (1 paper, 2018). "Cells expressing the “stemness” markers Nestin and S100B were detected in middle ear cholesteatoma and auditory canal skin." (PMID 29670222, 2018). "Using immunohistochemical analysis, cells expressing the stem cell marker Nestin were detected in the auditory canal skin, located within the lamina propria and within the matrix and perimatrix of middle ear cholesteatoma tissue." (PMID 29670222, 2018).
mood disorder (1 paper, 2020). A cognitive disorder a disturbance in which the person's mood is hypothesized to be the main underlying feature. "We report that 10 days of CSDS exposure to C57BL/6 and Nestin-GFP mice (in C57BL/6 and 129 mixed backgrounds) induces mood disorders, affects proliferation of neural stem or progenitor cells (NSCs/NPCs) in DG, and attenuates neurogenesis." (PMID 33182385, 2020).
muscular dystrophy (1 paper, 2018). Muscular dystrophy (MD) refers to a group of more than 30 genetic diseases characterized by progressive weakness and degeneration of the skeletal muscles that control movement. "Nestin(+)-cardiomyocytes were also detected in the adult mouse heart of a genetic model of muscular dystrophy lacking the structural proteins dystrophin and utrophin." (PMID 29492403, 2018).
Myocardial fibrosis (1 paper, 2025). "Our findings suggest that the absence of myocardial fibrosis and inflammation may be attributed to the activation and expansion of nestin-positive cell populations." (PMID 40869420, 2025).
Nausea (1 paper, 2024). A sensation of unease in the stomach together with an urge to vomit. "In conclusion, mice that are sensitized to CGRP (nestin/hRAMP1) mice show increased endogenous postural sway and are less sensitive to CGRP-receptor blockade in a nausea assay." (PMID 39652533, 2024).
nephritis (1 paper, 2025). Inflammation of renal tissue. "For example, the cytoskeleton protein nestin was found upregulated in the podocytes of MRL/lpr SLE mice, accompanied with enhanced mitophagy and oxidative stress; knockdown of nestin was able to suppress mitophagy and oxidative stress, reduce podocyte damage and alleviate nephritis in vivo." (PMID 40761479, 2025).
neural tumor (1 paper, 2018). "To determine the origin of TDECs in primary patient GBM (p-GBM), we first co-stained for ETV2 with neural stem-like cell markers (Nestin, Vimentin, and CD133) or mature neural tumor cell makers (NeuN and GFAP) in cryosections of p-GBM autopsies." (PMID 29527330, 2018).
neuroendocrine tumors (1 paper, 2022). "To identify neuroendocrine tumors in our cohort we have added various neuronal markers (i.e., NESTIN, TUBB2B, PEG10) to our gene classifier." (PMID 36230835, 2022).
NK/T-cell lymphoma (1 paper, 2021). "We identified four ENKTL markers (ZNF141, FCGR2C, NES and CDC27) in patients with extranodal NK/T-cell lymphoma." (PMID 34872521, 2021).
osteopetrosis (1 paper, 2023). Osteopetrosis, also known as marble bone disease, is a descriptive term that refers to a group of rare, heritable disorders of the skeleton characterized by increased bone density on radiographs. "We utilized Atp6i deficient mice as an osteopetrosis disease model to study tooth root formation and found that Atp6i knockout mice exhibit disrupted tooth root formation with truncated HERS progression as well as marked decreases in odontoblast markers Dspp, Nfic, Nestin, Osx, and Col1a1." (PMID 37599332, 2023).
peroxisome biogenesis disorder (1 paper, 2012). "As in patients with mild peroxisome biogenesis disorders who develop regressive changes, demyelination in cerebellum and brain stem preceded major myelin loss in corpus callosum of both Nestin-Pex5−/− and CMV-Tx-Pex5−/− mice." (PMID 22458306, 2012).
placenta previa (1 paper, 2021). "The expression of nestin was higher in placenta previa than in normal fetuses, and the authors concluded that nestin expression might be correlated with the clinicopathological characteristics of placenta previa." (PMID 34943921, 2021).
polycystic kidney disease (1 paper, 2025). A usually autosomal dominant and less frequently autosomal recessive genetic disorder characterized by the presence of numerous cysts in the kidneys leading to end-stage renal failure. "These analyses identified the glomerular compartment within the analyzed kidney section consisting of cells in cluster 17, with a subpopulation showing high nestin expression levels—a potential biomarker of mesangial expansion in this patient with polycystic kidney disease." (PMID 39075149, 2025).
Polyuria (1 paper, 2017). An increased rate of urine production. "In addition, neuron-specific Keap1 knockout mice (Keap1Flox/Flox::Nestin-Cre, Keap1-NKO) did not display polyuria." (PMID 28233855, 2017).
preeclampsia (1 paper, 2022). Preeclampsia is a hypertensive disorder of pregnancy that is characterized by new-onset hypertension with proteinuria presenting after 20 weeks of gestation, and depending on mild or severe forms may initially present with severe headache, visual disturbances, and hyperreflexia. "The highest observed to expected ratio value was seen for CDK5RAP2, a regulator of CDK5 (cyclin-dependent kinase 5) activity, which is implicated in preeclampsia via the regulation of Nestin, a cytoskeleton protein expressed in podocytes that serve as barriers to protein leakage." (PMID 35860693, 2022).
prion disease (1 paper, 2016). A transmissible disease that is caused by a protein that is able to induce abnormal folding of normal cellular proteins, leading to characteristic spongiform brain changes, which are associated with neuronal loss without an inflammatory response. "Brain expression levels of neuronal progenitor markers, nestin (Nestin), sex determining region Box 2 (Sox2), Class III beta-tubulin (Tuj1) decreased towards end-stage prion disease whereas doublecortin (Dcx) levels were less affected." (PMID 27886261, 2016).
progeria (1 paper, 2012). "However, m-SKPs derived from patients with progeria, a disease where accelerated ageing is observed expressed less nestin and versican, suggesting that progeria m-SKPs, assayed at the same time-point as normal m-SKPs had not developed to the same degree." (PMID 23226372, 2012).
prostate tumor (1 paper, 2018). "Oncomine data analysis comparing transcript expression of DPP4, TSPAN8, and NES between prostate tumor tissues and normal tissues revealed inconsistent upregulation of these genes in the different datasets." (PMID 30100995, 2018).
prostatic hyperplasia (1 paper, 2017). "These Tgfbr2 knockout data confirmed that increased TGF‐β activity in the stroma enhances recruitment of nestin+ cells for prostatic hyperplasia." (PMID 28191756, 2017). "Our study demonstrated that injection of 1D11 effectively reduced TGF‐β signaling, fibroblast numbers, and collagen deposition in prostatic hyperplasia mice with an accompanying reduction of the nestin+ cells in both prostatic stroma and blood." (PMID 28191756, 2017). "To further demonstrate that local excessive activation of TGF‐β recruits nestin+ cells to prostate stroma during pathogenesis of prostatic hyperplasia, we generated Nestin‐Cre-ER, Tgfbr2flox/flox mice by crossing Nestin‐Cre-ER with Tgfbr2flox/flox." (PMID 28191756, 2017). "To validate that recruited nestin+ cells from peripheral blood are involved in prostatic hyperplasia, we generated parabiotic pairs composed of Nestin‐Cre, Rosa26‐YFPflox/+ mice and wild‐type littermates (Para1 and Para3)." (PMID 28191756, 2017). "Nestin+ MSCs were increased in the prostatic hyperplasia mice." (PMID 28191756, 2017). "Thus, nestin+ cells were mobilized in blood circulation and recruited to the stroma in prostatic hyperplasia." (PMID 28191756, 2017). "To investigate whether high levels of active TGF‐β are involved in the recruitment of MSCs during prostatic hyperplasia, we used Nestin‐GFP transgenic mouse in which nestin+ cells were labeled with GFP." (PMID 28191756, 2017).
pulmonary diseases (1 paper, 2021). "Since we previously reported similar findings in lung cartilage, pluripotent nestin-positive cells capable of generating various types of lung tissue could exist, which may provide novel approaches to therapy for devastating pulmonary diseases." (PMID 34943921, 2021). "On the other hand, evidence also indicates that nestin-positive cells may have a role in tissue homeostasis and be capable of generating various types of lung tissues, which may provide novel therapeutic approaches for devastating pulmonary diseases." (PMID 34943921, 2021). "On the other hand, nestin could also participate in the pathogenesis of lung diseases in which there is no direct relationship with the heart, such as those described in the preceding paragraphs." (PMID 34943921, 2021).
RASopathies (1 paper, 2025). "Consistent with our findings in Nestin;BRAFKE/+ mice, mouse models carrying the BRAF V600E mutation showed multiple RASopathy-like phenotypes and also exhibited increased GFAP+ cells in the hippocampus and cortex, regardless of their genetic background." (PMID 39964758, 2025). "Taken together, these results demonstrate that Nestin;BRAFKE/+ mice recapitulate structural and intellectual deficits associated with RASopathies." (PMID 39964758, 2025). "Since several studies also have reported an imbalance in the neuron-glial population in RASopathy-related animal models, we investigated whether neuronal or glial cells were affected in Nestin;BRAFKE/+ animals." (PMID 39964758, 2025). "Therefore, Nestin;BRAFKE/+ mice are an ideal model for developmental diseases such as RASopathy." (PMID 39964758, 2025).
rectal tumors (1 paper, 2013). "In ND-GFP nude mice, GFP expression is under the control of the of the nestin promoter in which host-derived ND-GFP-expressing blood vessels were visualized in the early stage rectal tumors formed from CT26-RFP cells." (PMID 24265772, 2013).